HPGDS (hematopoietic prostaglandin D synthase)
Diseases named in the same sentence as HPGDS in open-access papers (continued):
Sharing a sentence is not in itself a finding about the gene and the disease.
eosinophilic esophagitis (1 paper, 2022). Eosinophilic esophagitis (EoE) is a chronic, allergic disease of the esophagus characterized clinically by symptoms of esophageal dysfunction (including vomiting, dysphagia, feeding disorders, food impaction and abdominal pain) which persist after treatment with proton pump inhibitors (PPIs). "Recently, a single cell analysis of T cells isolated from eosinophilic esophagitis (EoE) tissue in humans identified a pathogenic Th2 cell population that expresses HPGDS, CRTH2, and CD161." (PMID 36016937, 2022).
germ cell tumor (1 paper, 2022). A benign or malignant, gonadal or extragonadal neoplasm that originates from germ cells. "According to a genome-wide association study, HPGDS was significantly associated with germ cell tumors in the testis." (PMID 36553500, 2022).
Granuloma (1 paper, 2024). A compact, organized collection of mature mononuclear phagocytes, which may be but is not necessarily accompanied by accessory features such as necrosis. "Besides eosinophils and various inflammatory cell types, hepatic stellate myofibroblasts of the S. mansoni-driven granuloma express hPGDS and are notable sources of PGD2." (PMID 39173086, 2024).
myonecrosis (1 paper, 2025). "Our previous preliminary research indicated that our HPGDS inhibitor, PK007, decreases myonecrosis and retains mature (healthy) muscle fibres in mdx mice." (PMID 40275384, 2025).
myopia (1 paper, 2017). "Such expression changes were evident, particularly in the late myopia dataset where a wide range of genes linked with oxidative stress were either up-regulated (GPX1, GSTA3, MT-4, APOA1, OTUB, PTGDS, HSPB1, HSPB2) or down-regulated (XHD, SLC40A1, TF, SOD3, HPGDS, BCMO1)." (PMID 28852117, 2017).
polyarthritis (1 paper, 2013). "We have recently shown that dietary fortification with vitamin D3 reduced the severity and duration of adoptively transferred polyarthritis in rats and that the effect was associated with reduced expression of PGE synthase and increased expression of hPGDS by DCs from synovium-rich hind paw tissue." (PMID 23737645, 2013). "We have shown that dietary fortification with vitamin D3 reduced the severity and duration of adoptively transferred polyarthritis (ATA) in rats, and this was associated with increased expression of hPGDS and reduced expression of PGES by mDC from synovium-rich hind paw tissue of arthritic rats." (PMID 23737645, 2013).
stomach adenocarcinoma (1 paper, 2022). "On the other hand, a high level of HPGDS expression was significantly correlated with low disease-free survival (DFS) in stomach adenocarcinoma (STAD) patients." (PMID 36291099, 2022).
cancer (193 papers, 1991 to 2025). A tumor composed of atypical neoplastic, often pleomorphic cells that invade other tissues. "This association may provide some explanation for the association between increased expression of HPGDS and worse patient prognoses in some cancers." (PMID 36291099, 2022). "In our study, a TCGA-based analysis also yielded consistent results in that HPGDS was found to exhibit significant reductions at the mRNA and protein levels in these cancer types." (PMID 36291099, 2022). "The results showed that the expression levels of HPGDS were significantly increased or decreased in a variety of cancers." (PMID 36291099, 2022). "Considering the downregulation of HPGDS expression at the mRNA and protein levels in UCEC, HPGDS may play a role in inhibiting tumor progression in this cancer type." (PMID 36291099, 2022). "Therefore, stimulating the HPGDS/PGD2 axis could be a beneficial strategy in cancer, with TATEs serving as an additional biomarker." (PMID 28770200, 2017). "In this study, in order to gain an in-depth understanding of the roles of HPGDS, GSTZ1, and GSTA1—the less-studied members of the GST family—in tumorigenesis and development, we first performed a pan-cancer bioinformatics analysis." (PMID 36291099, 2022).
tumor (116 papers, 1989 to 2025). "Ischemia very interestingly appears to slowly breach through this coping mechanism by causing a decrease in tumor survival-critical proteins such as NUDT1, ELOVL5, HPGDS or DZIP3." (PMID 39327466, 2024). "H-PGDS/HPGDS expression is downregulated in five tumor types and upregulated in an equal number of tumor types." (PMID 36765904, 2023). "Presently, tumor studies on HPGDS are limited, and many studies report them as tumor suppressor genes." (PMID 36324576, 2022). "HPGDS plays a role in promoting tumor progression by regulating the level of cellular GSH and the activation of the JNK pathway in GMB." (PMID 36291099, 2022). "Specifically, the high expression of HPGDS in GBM indicate that this enzyme may have a tumor-promoting effect." (PMID 36291099, 2022). "There are two studies indicating that high expression of HPGDS might inhibit tumor proliferation in normal human cells." (PMID 32211020, 2020). "In terms of cell composition results of the GO analysis, HPGDS was found to be mainly involved in the movement of myofilaments and the cytoskeleton, which may suggest the role of HPGDS in migration and invasion of tumor cells." (PMID 36291099, 2022). "Firstly, relative genes involved in PGD2 signaling axis, HPGDS, PTGDS, PTGDR and SLCO2A1, were all significantly lower expressed in tumor lung tissue compared to normal in TCGA-LUAD cohort." (PMID 40474982, 2025). "It is worth noting that in a study on LGG, researchers found that HPGDS may act as a downstream target of miR-326 to promote the proliferation of LGG and regulate tumor apoptosis through the arachidonic acid metabolic pathway." (PMID 36291099, 2022).
infection (98 papers, 2008 to 2026). The state of being infected such as from the introduction of a foreign agent such as serum, vaccine, antigenic substance or organism. "Notable exceptions include several CD4+ T cell-associated genes (including HPGDS and MYD88), which were transiently upregulated during the ramp-up and peak stages of infection." (PMID 32119719, 2020). "This study also showed that hPGDS expressing immune cells were present immediately after infection while at later time points bronchial epithelial cells upregulated hPGDS and PGD2 production." (PMID 31226822, 2019). "Variation in hPGDS expression was minimal throughout the course of infection." (PMID 39818970, 2025).
respiratory disease (4 papers, 2007 to 2024). "Finally, in a study published recently, corticosteroid treatment was shown to downregulate hPGDS and DP2 expression in aspirin exacerbated respiratory disease." (PMID 33919453, 2021). "Furthermore, eosinophils isolated from patients with aspirin exacerbated respiratory disease produce more PGD2 and express higher levels of hPGDS." (PMID 33919453, 2021). "In aspirin-exacerbated respiratory disease, hPGDS-expressing eosinophils seem to contribute to elevated PGD2 levels as well as in allergic inflammation, which could be blocked with the hPGDS inhibitor HQL-79." (PMID 31226822, 2019).
cancers of the digestive system (2 papers, 2022 to 2024). "Previous research on HPGDS has mainly focused on cancers of the digestive system, and it has been studied in large part for the role of HPGDS in the production of the anti-inflammatory factor PGD2." (PMID 36291099, 2022).
inflammation (2 papers, 2021 to 2022). Aberrant reaction of the microcirculation characterized by movement of fluid and leukocytes from the blood into extravascular tissues. "Here, we sought to investigate the source and role of hPGDS-derived PGD2 in acute pulmonary inflammation." (PMID 34769126, 2021). "Hematopoietic PGD synthase (hPGDS) and its derived prostaglandin D2 (PGD2) are pro-inflammatory mediators produced by immune cells under stimulation and are often expressed in the early stage of respiratory inflammation." (PMID 36550973, 2022). "Notably, resident CD68+ macrophage populations express hPGDS at even higher levels than mast cells, as estimated by immunofluorescence staining, emphasizing that resident macrophages likely contribute to elevated PGD2 levels in acute lung inflammation." (PMID 34769126, 2021).
HPGDS also shares sentences with these, for which no sentence is quoted: diabetes (26 papers); prostate carcinoma (20); glaucoma (15); ovarian carcinoma (15); Parkinson disease (14); colon carcinoma (13); melanoma (13); neurodegenerative disease (11); leukemia (10); Hypertension (9); hepatocellular carcinoma (8); viral infections (8); fungal infection (7); liver cancer (7); periodontitis (7); cardiovascular diseases (6); cervical cancer (6); gastric cancer (6); liver diseases (6); Multiple Myeloma (6); acute kidney injury (5); autism spectrum disorder (5); bacterial infection (5); chronic obstructive pulmonary disease (5); endometriosis (5); hyperlipidemia (5); myocardial infarction (5); osteosarcoma (5); psoriasis (5); schistosomiasis (5).
A further 232 diseases each share a sentence with HPGDS in 5 papers or fewer.